REN (renin)
Diseases named in the same sentence as REN in open-access papers (continued):
Sharing a sentence is not in itself a finding about the gene and the disease.
cognitive decline (17 papers, 2014 to 2025). "ACE and REN, while central to cardiovascular regulation, have been linked to cognitive decline through RAS dysregulation in the brain." (PMID 40699836, 2025). "The renin–angiotensin system also contributes to brain damage and cognitive decline caused by chronic cerebral ischemia." (PMID 35455468, 2022). "The activation of renin-angiotensin system can lead to cognitive decline and brain damage caused by chronic cerebral ischemia." (PMID 34248489, 2021). "As the protective effect of antihypertensive agents on cognitive decline beyond their blood pressure-lowering effects has emerged, the potential effect of reducing the risk of AD via the renin-angiotensin system has been demonstrated in animal and human studies." (PMID 36949774, 2023). "Additionally, we focus on the role of polymorphisms within the genes for catechol-O-methyltransferase (COMT), apolipoprotein E (APOE), vascular endothelial growth factor (VEGF), and for renin-angiotensin-aldosterone system components, and their contribution to cognitive decline in PD." (PMID 33802165, 2021). "The cognitive decline and AD registered in CKD patients may be explained by the susceptibility of brain tissue to vascular dysfunction, inflammation, oxidative stress, and the renin–angiotensin–aldosterone system." (PMID 32824404, 2020). "The classical renin–angiotensin system (RAS), known as the angiotensin (Ang)-converting enzyme (ACE)/Ang II/Ang II type 1 (AT1) receptor axis, induces various organ damages including cognitive decline." (PMID 28721275, 2016).
lung carcinoma (17 papers, 2014 to 2025). "Renin-angiotensin system blockers (RASBs), which include angiotensin-converting enzyme inhibitors (ACEIs) and angiotensin-2 receptor 1 blockers (ARBs), have been reported to be associated with lung cancer metastasis, radiotherapy and chemotherapy." (PMID 31844581, 2019). "Multiple studies showed that the renin-angiotensin system (RAS) plays an important role in lung cancer." (PMID 39450258, 2024). "A KEGG pathway analysis showed enrichment for hematopoietic cell lineage, Staphylococcus aureus infection, and renin secretion pathways in both breast cancer and lung cancer." (PMID 32799825, 2020). "AGTR1 is primarily involved in the renin-angiotensin system and has previously been validated as an important tumor suppressor in lung cancer, cholangiocarcinoma, colon cancer and liver cancer." (PMID 28178311, 2017). "While further research is necessary to conclusively demonstrate a link between the renin-angiotensin system and lung cancers, the results suggest that the renin-angiotensin system plays a role in the pathology of adenocarcinoma." (PMID 28791183, 2017). "Here, we review current knowledge on the renin-angiotensin system (RAS), considering its potential modulatory role on cancer cell phenotype and on immune surveillance, while exploring the mechanistic association with lung cancer." (PMID 32503281, 2020). "This manuscript reviews the literature supporting a role for the renin-angiotensin system in the lung tumor microenvironment and discusses whether blockade of this pathway in clinical settings may serve as an adjuvant therapy in lung cancer." (PMID 32503281, 2020). "Current evidence highlights the significant involvement of the renin-angiotensin-aldosterone system (RAS) in tumorigenesis, particularly in lung cancer." (PMID 41271670, 2025). "Antihypertensive drugs that act on the renin-angiotensin pathway suppressed NNK-mediated tumorigenesis in mice, highlighting the possibility of preventing lung cancer with existing drugs." (PMID 37258578, 2023). "After such treatment of lung carcinoma cells A549, the levels of the ACE2 protein and renin were analyzed by western blotting." (PMID 33203793, 2020). "Duration of drugs for peptic ulcer and GORD, beta-blocking agents, and agents acting on the renin-angiotensin system and lung cancer presented a v-shaped nonlinear nominal significant association (P < 0.05)." (PMID 38487860, 2024). "The renin-angiotensin system is also involved in certain cancers, and researchers led by Ho-Young Lee at Seoul National University, South Korea, have shown how a tobacco-derived carcinogen called NNK promotes lung cancer via this pathway." (PMID 37258578, 2023). "Interestingly, the highest level of the renin protein occurred in intestinal cells and lung carcinoma cells but not in embryonic kidney cells HEK293." (PMID 33203793, 2020). "Interestingly, cathepsin D and TPA, but not chymase, renin and ACE (not shown), were expressed in both A549 and H460 lung cancer cells and TPA levels were upregulated in NSCLC cells, as compared with NHBE cells." (PMID 33380422, 2021).
malaria (17 papers, 2015 to 2026). Malaria is a serious and sometimes fatal disease caused by a parasite that commonly infects a certain type of mosquito which feeds on humans. "Increased renin levels have been linked to acute kidney injury and mortality in children with severe malaria or sickle cell anemia." (PMID 39492784, 2024). "Individuals of African descent have higher levels of circulating angiotensin-II due to its protective effects on malaria, thus genetic positive selection of the variants in the renin-angiotensin-aldosterone system may have been driven by malaria." (PMID 29079553, 2017). "In eukaryotes, the aspartic protease renin plays a role in hypertensive action, cathepsin D in tumorigenesis, plasmepsins in the degradation of human hemoglobin, which is required by Plasmodium falciparum, the causative agent of malaria and pepsin in the hydrolysis of acid-denatured proteins." (PMID 26287174, 2015). "FGA is a structural component of the extracellular matrix, while ALB is involved in oxygen binding; IL10 in African trypanosomiasis signaling and the malaria signaling pathway, and REN in the renin angiotensin system signaling pathway." (PMID 36762194, 2023). "Emerging evidence suggests that SARS-CoV-2 may influence malaria pathogenesis through dysregulation of the renin-angiotensin system." (PMID 41758897, 2026). "In addition, this study indicated that the lower expression of ANXA2 protein might also activate asthma, ECM-receptor interaction, leishmaniasis, malaria, and renin-angiotensin system (RAS) pathways, all of which might potentially regulate HCM treatment." (PMID 38277535, 2024).
myocardial ischemia (17 papers, 2009 to 2025). A disorder of cardiac function caused by insufficient blood flow to the muscle tissue of the heart. "Emerging evidence has revealed that the local RAS plays critical roles in the pathogenesis of cardiovascular disease, and ns-renin was reported to increase in the myocardium after myocardial ischemia." (PMID 29295576, 2017). "Myocardial ischemia induces activation of various components of the renin-angiotensin system (RAS), including angiotensinogen, renin, angiotensin-converting enzyme, angiotensins, and angiotensin receptors, in the acute phase of MI and in the postinfarction remodeling process." (PMID 23997803, 2013). "Similarly, cardiac fibrosis, the activation of renin–angiotensin–aldosterone system (RAAS) and myocardial ischemia/hypoxia may partly explain the upregulation of miR-98 in HCM." (PMID 37391825, 2023).
pulmonary fibrosis (17 papers, 2004 to 2025). Chronic progressive interstitial lung disorder characterized by the replacement of the lung tissue by connective tissue, leading to progressive dyspnea, respiratory failure, or right heart failure. "Although the pro-fibrotic activity of Ang II is well established, there are studies in the literature that suggest renin itself can directly cause lung fibrosis independently of Ang II19." (PMID 26494430, 2015). "Therefore, it is unlikely that pulmonary blood pressure is the cause of pulmonary fibrosis in RenTgMK mice, but the effect of high artery blood pressure and high renin activity on the development of pulmonary fibrosis needs to be addressed." (PMID 26494430, 2015). "Furthermore, oestrogen deficiency induces pathological activation of the renin-angiotensin system, resulting in up-regulated expression of pro-fibrotic mediators and initiation of a self-perpetuating fibrotic cascade that ultimately promotes pulmonary fibrosis pathogenesis." (PMID 40878468, 2025). "In chronic vitamin D deficient mice, triggering of the renin-angiotensin system (RAS) led to activation of TGFβ1 and pulmonary fibrosis." (PMID 36835058, 2023). "To further test the relationship between RAS activation and lung fibrosis, we gave RAS blockers, including the renin blocker aliskiren and the AT1R blocker losartan, to the vitamin D deficient mice and observed their effect on lung fibrosis." (PMID 28607392, 2017). "This study demonstrated that chronic VDD resulted in lung fibrosis, partly through the activation of the renin-angiotensin system." (PMID 28607392, 2017). "Here we show that transgenic mice expressing active renin from the liver (RenTgMK) developed progressive pulmonary fibrosis leading to impaired pulmonary function." (PMID 26494430, 2015). "The renin-angiotensin system has been suggested to play a role in the pathogenesis of lung fibrosis following lung injury." (PMID 26494430, 2015). "The AT1 blocker losartan and the renin blocker Aliskiren could alleviate lung fibrosis induced by chronic VDD." (PMID 28607392, 2017). "Recent studies have indicated that a local renin-angiotensin system could also be involved in the development of lung fibrosis." (PMID 15571627, 2004). "Angiotensinogen (AGT) is an precursor in tissue renin-angiotensin system (RAS) that plays an important role in promoting the development of hepatic fibrogenesis, renal interstitial fibrosis, and idiopathic pulmonary fibrosis." (PMID 34424905, 2021). "The renin antagonist aliskiren and the AT1R blocker losartan could significantly rescue the tissue damage and alleviate lung fibrosis." (PMID 28607392, 2017). "SARS-CoV-2 virus binds to angiotensin converting enzyme 2 (ACE2) and alters renin-angiotensin system activities, thus leading to enhanced inflammation (increased levels of VEGF, IP-10/CXCL10, MCP-3/CCL7, IL-6, IL-1, ROS etc.)and development of pulmonary fibrosis." (PMID 35139898, 2022).
breast carcinoma (16 papers, 2006 to 2025). "Gene expression studies have found pathways related to the renin-angiotensin system and focal adhesion to be significantly associated with prognosis of breast cancer." (PMID 21062454, 2010). "Whilst ACE inhibitors and ARBs have been proposed to affect breast cancer through their impact on the renin‐angiotensin system, meta‐analyses across smaller studies are inconsistent." (PMID 41163361, 2025). "Only a few pathways were distinctively diverse within each subtype, and these were the same in all breast cancer subtypes (linoleic acid metabolism, renin/angiotensin system, and neuroactive ligand/receptor interaction)." (PMID 25294321, 2014). "In lobular carcinoma in situ, positive staining for (pro)renin was observed in myoepithelial cells and connective tissues surrounding the lobules." (PMID 16755291, 2006). "We developed an AngII peptide intending to assess whether the peptide of the renin–angiotensin system holds the ability to target AT1 receptor-overexpressing breast cancer in vivo." (PMID 38004416, 2023). "Renin-angiotensin system (RAS) G-protein coupled receptors (GPCRs) in breast cancer." (PMID 25741281, 2015). "Furthermore, given the widespread clinical use of ACE inhibitors, this research may also reveal unintended effects of modulating the renin–angiotensin system on tumor progression, thereby informing safer and more personalized treatment strategies in breast cancer patients." (PMID 40710006, 2025). "For other targets including annexin A5 (ANXA5), prothrombin (F2) and renin (REN), there was no firm evidence to link their functions directly to breast cancer progression, and they were less significant in the PPI network, which meant that they might be not important targets for LF triterpenoids." (PMID 33246450, 2020). "Another study demonstrates that the RAS components, angiotensinogen, renin, ACE and AT1R are expressed in hormone-receptor negative and ER+ve human breast cancer tissue, as well as in representative human breast cancer cells." (PMID 28416734, 2017).
Hypercholesterolemia (16 papers, 2011 to 2026). An increased concentration of cholesterol in the blood. "For example, hypercholesterolemia can stimulate the renin–angiotensin–aldosterone system, increasing levels and activity of Ang I, Ang II, and endothelin-1, which may lead to the elevation of blood pressure." (PMID 34336961, 2021). "Activation of the renin-angiotensin system by hypercholesterolemia may further activate the sympathetic nervous system through a variety of mechanisms." (PMID 24667944, 2014). "However, we cannot rule out the participation of other hypercholesterolemia-induced factors contributing to the renal dysfunction, including reduced nitric oxide bioavailability, exacerbation of the renin-angiotensin system and increased oxidative stress." (PMID 22117541, 2011).
chronic obstructive pulmonary disease (15 papers, 2012 to 2025). A chronic and progressive lung disorder characterized by the loss of elasticity of the bronchial tree and the air sacs, destruction of the air sacs wall, thickening of the bronchial wall, and mucous accumulation in the bronchial tree. "While there is little information on activity of the renin-angiotensin system in patients with chronic obstructive pulmonary disease one could speculate that Ang II contributes to these changes." (PMID 22276172, 2012). "Interestingly, regulation of renin–angiotensin II systems by ACE2 is also crucial for the pathogenesis of chronic obstructive pulmonary diseases (COPD)." (PMID 32698440, 2020).
Hypomagnesemia (15 papers, 2018 to 2025). An abnormally decreased magnesium concentration in the blood. "A further speculation is that alterations in blood electrolytes and pH associated with Gitelman’s syndrome, i.e., hypomagnesemia, hypocalciuria, hypochloremia, and hypokalemic alkalosis, underlie possible compromised renin–angiotensin II–aldosterone pathway." (PMID 31543812, 2019).
renal cell carcinoma (15 papers, 2014 to 2025). "Other entities, such as Wilms tumor, renal cell carcinoma, and renal oncocytoma, can also elevate renin levels and appear as complex renal masses on imaging." (PMID 40989803, 2025). "This change can have an impact on kidney function through several pathways such as metabolism, renal cell carcinoma, the renin–angiotensin system, and the transport and catabolism systems, which is in line with Rite’s “gut–kidney axis” theory." (PMID 36615439, 2022). "By means of GSEA, we identified five ADAMTS14-related signaling pathways, including MTOR, PPAR, INSULIN signaling pathway, renal cell carcinoma, and renin–angiotensin system." (PMID 35572505, 2022). "Renal cell carcinoma can directly cause HTN by the formation of arteriovenous fistula, tumor compression-induced renin secretion, ectopic hormone syndromes, paraneoplastic vasculitis, and brain metastasis." (PMID 35252390, 2022). "hsa-let-7f: Endometrial cancer, Renin secretion, Renal cell carcinoma, Colorectal cancer, Human cytomegalovirus infection, Thyroid hormone signaling pathway, Long-term depression, Cocaine addiction, Prostate cancer, Neurotrophin signaling pathway." (PMID 34187521, 2021). "According to the threshold of the |NES| >1.5 and nominal p-value < 0.05, we identified five signaling pathways that showed significantly different enrichment in the ADAMTS14 expression phenotype, including INSULIN, MTOR, PPAR, renal cell carcinoma, and renin–angiotensin system pathways." (PMID 35572505, 2022). "Renin positivity may also be observed in some cases of Wilms’ tumor (WT-1 staining), renal cell carcinoma (RCC), or renal oncocytoma." (PMID 25177679, 2014). "hsa-mir-26b: Endometrial cancer, Small cell lung cancer, Renal cell carcinoma, Melanoma, Amyotrophic lateral sclerosis (ALS), Chronic myeloid leukemia, Human T-cell leukemia virus 1 infection, Renin secretion, Cocaine addiction, Colorectal cancer." (PMID 34187521, 2021). "For instance, in clear cell renal cell carcinoma (CC-RCC), there is a notable increase in the levels of renin and angiotensin-converting enzyme (ACE), a phenomenon also observed in other cancers such as reninoma, where renin levels exceed those found in normal tissues." (PMID 41301459, 2025).
adrenal adenoma (14 papers, 2015 to 2026). "Diagnostic workup included elevated transtubular potassium gradient and aldosterone-to-renin ratio, confirmed by computed tomography imaging showing a typical left adrenal adenoma." (PMID 40585927, 2025). "Of the 10 cases which consistently lateralised, all were subsequently confirmed histologically as adrenal adenomas, with eight (80%) demonstrating normalisation of aldosterone‐to‐renin ratios and all achieving normokalaemia following unilateral adrenalectomy." (PMID 39207956, 2024). "Patients who were referred to the endocrinology clinic for adrenal incidentaloma between 2014 and 2019 were assessed with 1 mg dexamethasone suppression test, 24-h urine metanephrines and normetanephrines, plasma aldosterone to renin ratio." (PMID 36326332, 2022). "Indeed, medical imaging showed renal artery stenosis and adrenal adenoma, respectively; thereby explaining renin and aldosterone levels." (PMID 41584271, 2026). "A 24-hour urinary specimen for measurement of catecholamines, 1 mg overnight dexamethasone suppression test, and if patient is hypertensive, a ratio of serum aldosterone concentration/plasma renin activity are routinely used to understand the functionality of the adrenal incidentaloma." (PMID 26101674, 2015). "Guthrie and Kotchen reported a similar case with a unilateral adrenal adenoma producing both cortisol and aldosterone, in which renin was not suppressed by aldosterone, same as in this patient." (PMID 31208392, 2019).